SQSTM1 (sequestosome 1)
Description:
Molecular adapter required for selective macroautophagy (aggrephagy) by acting as a bridge between polyubiquitinated proteins and autophagosomes. Promotes the recruitment of ubiquitinated cargo proteins to autophagosomes via multiple domains that bridge proteins and organelles in different steps. SQSTM1 first mediates the assembly and removal of ubiquitinated proteins by undergoing liquid-liquid phase separation upon binding to ubiquitinated proteins via its UBA domain, leading to the formation of insoluble cytoplasmic inclusions, known as p62 bodies. SQSTM1 then interacts with ATG8 family proteins on autophagosomes via its LIR motif, leading to p62 body recruitment to autophagosomes, followed by autophagic clearance of ubiquitinated proteins. SQSTM1 is itself degraded along with its ubiquitinated cargos. Also required to recruit ubiquitinated proteins to PML bodies in the nucleus. Also involved in autophagy of peroxisomes (pexophagy) in response to reactive oxygen species (ROS) by acting as a bridge between ubiquitinated PEX5 receptor and autophagosomes. Acts as an activator of the NFE2L2/NRF2 pathway via interaction with KEAP1: interaction inactivates the BCR(KEAP1) complex by sequestering the complex in inclusion bodies, promoting nuclear accumulation of NFE2L2/NRF2 and subsequent expression of cytoprotective genes. Promotes relocalization of 'Lys-63'-linked ubiquitinated STING1 to autophagosomes. Involved in endosome organization by retaining vesicles in the perinuclear cloud: following ubiquitination by RNF26, attracts specific vesicle-associated adapters, forming a molecular bridge that restrains cognate vesicles in the perinuclear region and organizes the endosomal pathway for efficient cargo transport. Sequesters tensin TNS2 into cytoplasmic puncta, promoting TNS2 ubiquitination and proteasomal degradation. May regulate the activation of NFKB1 by TNF, nerve growth factor (NGF) and interleukin-1. May play a role in titin/TTN downstream signaling in muscle cells. Adapter that mediates the interaction between TRAF6 and CYLD (By similarity).
Synonyms: EBIAP; p60; p62; OSIL; p62B; A170; DMRV; FTDALS3; NADGP; PDB3; ZIP3
Tractability: Small molecule: a structure with a bound ligand is known; a high-quality ligand is known. PROTAC: UniProt records ubiquitination sites on it; ubiquitination databases record sites on it; its protein half-life has been measured; a small molecule that binds it is known.
Gene: Protein-coding gene on chromosome 5 (179,806,398 to 179,838,078, forward strand). Ensembl gene ENSG00000161011.
Subcellular location: Cytoplasmic vesicle, autophagosome; Preautophagosomal structure; Cytoplasm, cytosol; Nucleus, PML body; Late endosome; Lysosome; Nucleus; Endoplasmic reticulum; Cytoplasm, myofibril, sarcomere
Subcellular location (Human Protein Atlas): Cytosol; Vesicles
Pathways (Reactome):
Signal Transduction: NF-kB is activated and signals survival; NRIF signals cell death from the nucleus; p75NTR recruits signalling complexes
Autophagy: PINK1-PRKN Mediated Mitophagy; Pexophagy
Cellular responses to stimuli: KEAP1-NFE2L2 pathway; Nuclear events mediated by NFE2L2
Disease: Signaling by ALK fusions and activated point mutants
Immune System: Interleukin-1 signaling
Metabolism of proteins: Neddylation
Gene Ontology:
Molecular function: enzyme binding; identical protein binding; K63-linked polyubiquitin modification-dependent protein binding; molecular condensate scaffold activity; molecular sequestering activity; protein binding; protein kinase binding; protein kinase C binding; protein sequestering activity; protein-macromolecule adaptor activity; SH2 domain binding; signaling adaptor activity; signaling receptor activity; ubiquitin binding; ubiquitin protein ligase binding; ubiquitin-modified protein reader activity; ionotropic glutamate receptor binding; receptor tyrosine kinase binding; protein-containing complex binding; zinc ion binding
Biological process: aggrephagy; autophagy; cellular response to stress; endosome organization; macroautophagy; membraneless organelle assembly; mitophagy; negative regulation of ferroptosis; negative regulation of protein ubiquitination; negative regulation of toll-like receptor 4 signaling pathway; pexophagy; positive regulation of autophagy; protein catabolic process; protein localization to perinuclear region of cytoplasm; protein targeting to vacuole involved in autophagy; regulation of canonical NF-kappaB signal transduction; regulation of protein complex stability; response to mitochondrial depolarisation; autophagy of mitochondrion; endosomal transport; intracellular protein localization; intracellular signal transduction; positive regulation of apoptotic process; positive regulation of long-term synaptic potentiation; positive regulation of protein localization to plasma membrane; and 10 more
Cellular component: amphisome; autolysosome; autophagosome; cytoplasm; cytoplasmic ribonucleoprotein granule; cytosol; endoplasmic reticulum; extracellular exosome; inclusion body; intracellular membraneless organelle; late endosome; lysosome; nucleus; phagophore assembly site; PML body; aggresome; nucleoplasm; glutamatergic synapse; Lewy body; mitochondrion; sarcomere; sperm midpiece; synapse
Genetic constraint (gnomAD): Loss-of-function variants: 36 observed, 42.09 expected, observed/expected ratio (o/e) 0.86, 90% interval 0.65 to 1.13. The synonymous counts are far from expectation, so gnomAD's model fits this gene poorly and the ratio says little. Missense variants: 617 observed, 592.22 expected, observed/expected ratio (o/e) 1.04, 90% interval 0.97 to 1.11. Synonymous variants: 290 observed, 234.02 expected, observed/expected ratio (o/e) 1.24, 90% interval 1.12 to 1.37.
Gene-disease validity (ClinGen):
ClinGen rates the evidence that SQSTM1 causes each of these diseases.
frontotemporal dementia and/or amyotrophic lateral sclerosis 3 (autosomal dominant): Moderate.
Homologues: Orthologues: chimpanzee SQSTM1 (99% identical), macaque SQSTM1 (98% identical), pig SQSTM1 (93% identical), rabbit SQSTM1 (93% identical), rat Sqstm1 (91% identical), mouse Sqstm1 (91% identical), dog SQSTM1 (90% identical), guinea pig SQSTM1 (72% identical), tropical clawed frog sqstm1 (55% identical), zebrafish sqstm1 (47% identical), Drosophila melanogaster ref(2)P (25% identical), Caenorhabditis elegans sqst-1 (20% identical), and 4 more.
Diseases named in the same sentence as SQSTM1 in open-access papers:
SQSTM1 is named in the same sentence as 303 diseases in open-access papers, as found by Europe PMC text mining. Sharing a sentence is not in itself a finding about the gene and the disease. The quoted sentences say what the papers report.
breast cancer (47 papers, 2010 to 2026). A primary or metastatic malignant neoplasm involving the breast. "The development of cancer, particularly pancreatic, hepatocyte, lung, gastric, and breast cancers, is strongly linked to the accumulation of SQSTM1/p62." (PMID 40231206, 2025). "Through comparison each gene of our gene signature with existing studies separately, we found that there are many studies on the association between gene PTGS2, gene SQSTM1 and breast cancer." (PMID 35436939, 2022). "SQSTM1 abnormal expression has been observed in hepatocellular, prostate and breast cancers and is associated with poor outcomes in breast cancer." (PMID 20441585, 2010). "Meanwhile, SQSTM1 is implicated in other numerous types of disorders, particularly, neurodegenerative, cardiometabolic disorders, melanomas and breast cancer." (PMID 36186436, 2022). "Taken together, these results indicate that accumulated MAP1LC3B and SQSTM1 caused by autophagy inhibition might be involved in the chemoresistance of breast cancer cell lines." (PMID 34829743, 2021). "Six ferroptosis-related genes (SLC7A11, GPX4, FTH1, NQO1, NFE2L2, SQSTM1) demonstrated consistent upregulation across all breast cancer subtypes, with higher expression observed in more aggressive tumors." (PMID 42074090, 2026). "This indicates that CDKN1A and MINK1 are downregulated in breast cancer relative to normal tissue, while SQSTM1 shows upregulation in the same comparison." (PMID 39963142, 2025). "Consistently, western blot analysis further revealed decreased expression of ATG, a reduced ratio of LC3-II to LC3-I, and increased SQSTM1 in breast cancer cells with TRPV2 knockdown." (PMID 39334351, 2024). "The autophagy adapter protein SQSTM1/p62 has been shown to be overexpressed in breast cancer, and this protein is considered as a metastasis-related protein." (PMID 38398197, 2024). "DCAF8 interacts with SQSTM1, whose expression has been associated with CSC properties in breast cancer." (PMID 36831395, 2023). "SQSTM1 was poorly immune-related, validating previous results that SQSTM1 regulates breast cancer metastasis from a tumor cell perspective." (PMID 35436939, 2022). "In particular, it has been observed that in breast cancer, E-cadherin physically interacts with p62/SQSTM1 to mediate LC3 targeting and consequent delivery to LC3-containing autophagosomes." (PMID 35721483, 2022). "In other words, SQSTM1 functioned from the perspective of tumor cells since it was significantly upregulated in metastatic breast cancer, and its knockdown attenuated the ability of tumor cells to invade metastases." (PMID 35436939, 2022). "The combination of CQ plus either ipatasertib or taselisib induced a more robust accumulation of LC3 and p62/SQSTM1 co-aggregates in all breast cancer models." (PMID 35761360, 2022). "The effects of cGAS or SQSTM1 expression on cell growth and survival of breast cancer cells were also clarified through silencing of either cGAS or SQSTM1 in the MCF-7, MDA-231 and BT-549 cells." (PMID 34123836, 2021). "Accumulated protein levels of MAP1LC3B and SQSTM1 in treated breast cancer cell lines were observed and quantified." (PMID 34829743, 2021). "The accumulated MAP1LC3B and SQSTM1 caused by autophagy inhibition increased chemosensitivity to cancer drugs (CIS and PTX) in breast cancer cell lines." (PMID 34829743, 2021). "The expression level of SQSTM1 positively correlates with the expression level of EGFR in breast cancer." (PMID 34830108, 2021). "was that p62/SQSTM1 improves breast cancer stem-like properties by promoting MYC mRNA stabilization." (PMID 35083142, 2021). "SQSTM1 is a key component and player in VANGL2–JNK signaling pathway and this signaling pathway is associated with the proliferation of breast cancer cells." (PMID 31311202, 2019).
breast cancer (continued). "More importantly, our findings implicate Pfkfb3 as an autophagy substrate that interacts physically with the cargo adaptor protein, p62/SQSTM1, thereby modulating the expression levels of Pfkfb3 in disseminated breast cancer cells." (PMID 31413316, 2019). "Our findings were consistent with a previous study on a traditional herbal medicine, SH003, which suppressed breast cancer growth by inducing autophagy through promoting p62/SQSTM1." (PMID 29315210, 2018). "The mRNA expression patterns of BECN1, ATG16L1 or SQSTM1 were also compared across different breast cancer subtypes." (PMID 28628113, 2017). "Upregulation of miR-20a strongly associates with downregulation of BECN1, SQSTM1 and ATG16L1 in human breast cancers, especially in triple-negative subtypes." (PMID 28628113, 2017). "Altogether, we provide compelling evidence that, in breast cancer cells, WNT5A–VANGL2 signalling requires the integrity of the VANGL2–p62/SQSTM1 complex to associate with and phosphorylate JNK." (PMID 26754771, 2016). "Altogether, these data suggest that the VANGL2–p62/SQSTM1 colocalization occurs in part in late endosomal compartments in breast cancer cells and is regulated by cell junction formation." (PMID 26754771, 2016). "We identify p62/sequestosome-1 (hereafter named p62/SQSTM1) as a novel VANGL2-binding partner in breast cancer cells." (PMID 26754771, 2016). "Western analyses were used to monitor the protein abundances of RRM2, LC3 and p62/SQSTM1, another autophagy marker, in breast cancer cells treated with TMX for 24 and 48 h." (PMID 26675256, 2016). "To test these findings in other tumor cell types, we expanded our analysis to a panel of breast cancer cell lines where we detected a range of p62/SQSTM1 protein expression (middle) and drug sensitivity to MK2206 (bottom)." (PMID 24599075, 2014). "In human breast cancer cells, the ubiquitin-binding protein SQSTM1/p62 and LC3B interact with caspase-8 to promote caspase-8 oligomerization, activation, and apoptosis." (PMID 23691463, 2012). "Moreover, western blotting analysis revealed an increase in ABCG2 and LC3-II accumulation, as well as a decrease in SQSTM1/p62 expression in breast cancer cells treated with CXCL1 for 24 h." (PMID 39394189, 2024). "Likewise, western blot analysis revealed increased expression of ATG, an elevated ratio of LC3-II to LC3-I, and decreased SQSTM1 in breast cancer cells upon TRPV2 activation by cannabidiol." (PMID 39334351, 2024). "Then, Western blot analysis was conducted to determine whether MA affects autophagy in breast cancer cells, and the findings showed that MA dose-dependently elevated the levels of autophagic substrate p62/SQSTM1 and autophagosome marker LC3-II." (PMID 36976201, 2023). "Based on this, we infered that SQSTM1 might play a role to breast cancer cell migration from the tumor cell perspective." (PMID 35436939, 2022). "Based on the results above, we could infer that SQSTM1 functioned from the perspective of tumor cells since it was significantly upregulated in metastatic breast cancer, and its knockdown attenuated the ability of tumor cells to invade metastases." (PMID 35436939, 2022). "The aberrant accumulation of SQSTM1 has been found in gastrointestinal cancer, prostate cancer, hepatocellular carcinoma, breast cancer and lung adenocarcinoma, suggesting that SQSTM1 accumulation through autophagy inhibition correlates with cancer progression." (PMID 34829743, 2021). "In addition, the accumulated MAP1LC3B and SQSTM1 proteins in breast cancer cell lines treated with autophagy inhibitors and their role in chemoresistance of breast cancer cell lines are studied." (PMID 34829743, 2021). "The accumulation of MAP1LC3B and SQSTM1 resulting from autophagy defects could facilitate chemosensitivity in breast cancer cell lines." (PMID 34829743, 2021). "Moreover, the physical closeness of E-cadherin and SQSTM1/p62 was demonstrated by proximity ligation assays in breast cancer cell lines and primary tumors." (PMID 32714931, 2020).
breast cancer (continued). "Since our study showed that CEP treatment induced the expression of SQSTM1 in breast cancer cells, we speculated that CEP may act as a potent autophagic flux inhibitor and inhibit autophagic degradation." (PMID 31699152, 2019). "miR-20a expression correlates negatively with that of BECN1, ATG16L1 or SQSTM1 in breast cancer." (PMID 28628113, 2017). "Therefore, it may be possible to target the SQSTM1 gene for high expression in the metastatic breast cancer group, providing a basis for drug development against tumor cells as targets." (PMID 35436939, 2022). "However, little is known about the role MAP1LC3B and SQSTM1 co-expression plays in breast cancer." (PMID 34829743, 2021). "However, the biological role and clinical significance of MAP1LC3B and SQSTM1 in breast cancer remains unclear." (PMID 34829743, 2021). "Moreover, we found that MAP1LC3B and SQSTM1 might be accumulated due to autophagy inhibition in breast cancer cell lines." (PMID 34829743, 2021). "In addition, SH003-induced p62/SQSTM1 could function as an important mediator for ROS generation-dependent cell death suggesting that SH003 may be useful for treating breast cancer." (PMID 29179443, 2017). "The selective autophagy receptor NBR1 (next to BRCA1 gene 1 protein) cooperates with SQSTM1/p62 to sequester ITCH, an E3 ubiquitin ligase that targets p63 for proteasomal degradation in breast cancer cells." (PMID 41009794, 2025). "Quantitative PCR analysis demonstrated a significant reduction in the expression levels of ATG, LC3A, and LC3B, along with an increase in SQSTM1, following TRPV2 knockdown in MCF-7, SK-BR-3, and MDA-MB-231 breast cancer cells." (PMID 39334351, 2024). "In contrast, the application of the TRPV2 agonist cannabidiol to MCF-7, SK-BR-3, and MDA-MB-231 breast cancer cells resulted in increased expression of ATG, LC3A, and LC3B, along with reduced SQSTM1, as observed in our quantitative PCR analysis." (PMID 39334351, 2024). "We constructed a novel 6-gene signature (SQSTM1, GDF9, LINC01125, PTGS2, GVINP1, and TMEM64) and used an XGBoost model to predict the metastatic status in breast cancer (AUC = 0.82)." (PMID 35436939, 2022). "After the CB-2 treatment, SQSTM1 and LC3B-II accumulated in NCI-H157 NSCLC cells and in other tumor cell types, including human breast cancer (BC) MCF-7 cells and hepatocellular carcinoma (HCC) HepG2 cells." (PMID 34440609, 2021). "A recent study reported that depletion of TRIM59 suppresses breast cancer metastasis by promoting RNFT1-induced K63 poly ubiquitination and SQSTM1-directed autophagic degradation of PDCD10." (PMID 31600735, 2019). "Compared with the normal mammary tissues, breast cancer tissues showed an obvious reduction in BECN1, ATG16L1 and SQSTM1 levels, whereas OPTN expression was higher in cancer tissues." (PMID 28628113, 2017). "Taken together, these data show that overexpression of VANGL2 in breast cancer cells correlates with JNK activation and cell proliferation, which is sensitive to inhibition of the VANGL2–p62/SQSTM1 interaction." (PMID 26754771, 2016). "Over the course of our study, we have identified a peptide able to destabilize the VANGL2–p62/SQSTM1 complex, and to impair JNK signalling and cell proliferation of breast cancer cells." (PMID 26754771, 2016). "The results obtained in breast cancer cells and in Xenopus show the existence of an evolutionarily conserved WNT5A–VANGL2–p62/SQSTM1–JNK signalling pathway." (PMID 26754771, 2016). "First, we compared the possibility to use P-LISA in breast cancer cells (MDA-MB-436) to detect the interaction between LC3B (an ATG8 family member) and SQSTM1 (a cargo adapter)." (PMID 26034986, 2015). "In contrast, genetic depletion of BECN1, ATG5, p62/SQSTM1, or LAMP1 or pharmacological inhibition by chloroquine, resensitizes breast cancer cells to PARPi by shifting DNA repair towards error‐prone NHEJ (non‐homologous end joining), leading to mitotic catastrophe and genomic instability." (PMID 41329030, 2025).
breast cancer (continued). "In conclusion, our present research constructed a novel 6-gene signature (SQSTM1, GDF9, LINC01125, PTGS2, GVINP1, and TMEM64) by feature importance score and used an XGBoost model to predict the metastatic status in breast cancer (AUC = 0.82, higher than the previous studies to our knowledge)." (PMID 35436939, 2022). "Astonishingly, the autophagy inhibitor accumulated the protein levels of MAP1LC3B/SQSTM1 and enhanced the cytotoxic effects of cisplatin and paclitaxel in MCF7 and BT474 breast cancer cell lines, implying that autophagy inhibition might result in poor prognosis and chemosensitivity in IDC." (PMID 34829743, 2021). "Taken together, these data indicated that DNA autophagy in breast cancer cells could be selective autophagy of cytoplasmic free DNA but not nucleophagy and possibly involved cGAS, SQSTM1 and LC3." (PMID 34123836, 2021). "Notably, however, nonsteroidal AIs (Letrozole and Anastrozole) did not increase LC3-I/II or suppress SQSTM1/p62 levels in cells, indicating that these treatments may not induce autophagy in breast cancer cells." (PMID 38567308, 2024). "However, the roles of MAP1LC3B and SQSTM1 in breast cancer are still not clear." (PMID 34829743, 2021). "In control mice not exposed to HF diet in utero, VPA/hydralazine increased mammary tumor incidence and burden, and elevated expression of the unfolded protein response and autophagy genes, including HIF-1α, NFkB, PERK, and SQSTM1/p62." (PMID 31889127, 2019).